CTNNB1 (catenin beta 1)
Diseases named in the same sentence as CTNNB1 in open-access papers (continued):
Sharing a sentence is not in itself a finding about the gene and the disease.
neuropathy (1 paper, 2022). A disorder affecting the nervous system that manifests with pain, tingling, numbness, and/or muscle weakness. "Moreover, the CTNNB1 network harbours proteins previously shown by us to be regulated in another neuropathy-model, i.e., evoked by spared-nerve-injury (SNI)." (PMID 35250568, 2022).
ocular surface squamous neoplasia (1 paper, 2015). "Zhang, Liu and co-workers proposed that conditional expression of a murine Ctnnb1 gene gain-of-function mutation alone caused corneal neoplasia and neovascularization, resembling human ocular surface squamous neoplasia (OSSN)." (PMID 26503156, 2015).
oligodendroglioma (1 paper, 2023). A well-differentiated (WHO grade II), diffusely infiltrating neuroglial tumor, typically located in the cerebral hemispheres. "We observed that there were statistically significant differences in OS according to the different expression levels of DKK3 and CTNNB1 in the LGG group excluding patients with oligodendrogliomas compared with those in the LGG group including patients with oligodendrogliomas." (PMID 37149563, 2023).
orofacial cleft (1 paper, 2019). A disorder of facial skeleton that is characterized by cleft lip and/or cleft palate that result in feeding, speech and hearing problems caused by failures during development. "However, de novo nonsense and frameshift mutations in the key canonical WNT signaling mediator gene catenin beta 1 (CTNNB1; encoding β-catenin) were linked with abnormal craniofacial features, but not with orofacial clefts." (PMID 30760477, 2019).
oropharyngeal dysphagia (1 paper, 2023). "Overall, our observation suggests that CTNNB1-mutated patients might show a reduced risk of oropharyngeal dysphagia and oral-motor dyspraxia, but struggle in developing a mature chewing pattern." (PMID 37895192, 2023).
osteoma (1 paper, 2022). A benign, well-circumscribed, bone-forming neoplasm predominantly composed of lamellar bone. "In order to get deeper insights into the biological differences of osteomas according to the CTNNB1 mutational status, we performed multiplex gene expression profiling employing the NanoString nCounter system." (PMID 34725446, 2022). "After RNA extraction and quality control, based on an mRNA expression analysis covering 770 genes from 13 essential cancer hallmark-associated canonical pathways, eight CTNNB1 mutated and four CTNNB1 wild type osteomas were comparatively analyzed." (PMID 34725446, 2022). "Our finding of recurrent CTNNB1 mutations in osteomas contributes to the concept of an outstanding role of WNT/β-catenin in bone biology and disease." (PMID 34725446, 2022). "Based on NanoString multiplex expression profiling performed in a subset of cases, CTNNB1-mutated osteomas segregated in a defined “WNT-cluster”, substantiating functionality of CTNNB1 mutations which are associated with β-catenin stabilization." (PMID 34725446, 2022). "This is in line with the results of our NanoString mRNA expression approach, providing evidence of distinct gene sets being expressed in osteomas with and without CTNNB1 mutation, respectively." (PMID 34725446, 2022). "According to the clinical data available, none of the patients (including those with a CTNNB1 wild type osteoma), had multiple osteomas or stigmata implying a syndromal association and thus potential involvement of the APC gene." (PMID 34725446, 2022). "In this focused analysis of a cohort of sporadic, non-syndromal osteomas, we have identified hotspot mutations in the CTNNB1 gene (encoding β-catenin) in 22 of 36 cases (61.1%)." (PMID 34725446, 2022). "Though the extractable information on individual genes is naturally limited, this approach provides evidence of distinct gene sets being expressed and biological pathways being activated in osteomas with and without CTNNB1 mutation, respectively." (PMID 34725446, 2022).
osteonecrosis (1 paper, 2024). A none disease characterized by death of bone tissue due to a lack of blood supply. "We also provided a Col2-specific Ctnnb1 knockout mouse model for the first time, which mimics full spectrum of osteonecrosis phenotype of GONFH." (PMID 38376133, 2024).
ovarian adenocarcinoma (1 paper, 2015). An adenocarcinoma that arises from the ovary. "Phenotypic features in an Apc- and Pten- mutant mouse ovarian adenocarcinoma model with respect to Ctnnb1 gene dosage." (PMID 26528816, 2015).
Ovarian insufficiency (1 paper, 2019). "Most importantly, ovarian insufficiency allows myometrial invasion of mutant epithelial cells that harbor a CTNNB1 exon 3 mutation." (PMID 30782821, 2019). "In addition, the CTNNB1 exon 3 mutation promotes the myoinvasion of EECs in collaboration with ovarian insufficiency." (PMID 30782821, 2019).
papillary adenocarcinoma (1 paper, 2023). A morphologic variant of adenocarcinoma.
paraganglioma (1 paper, 2025). A benign or malignant neoplasm arising from paraganglia located along the sympathetic or parasympathetic nerves. "When chromogranin and synaptophysin are negative with these paraganglioma-like features, a positive nuclear B-catenin and a point mutation of CTNNB1 can separate this tumor from radiologic and morphologic cellular and stromal mimickers." (PMID 39093425, 2025).
pediatric cancer (1 paper, 2024). "The analysis detected mutations in several cancer-related genes previously reported to be implicated in pediatric cancer, such as CTNNB1, WT1, AMER1, and NF1." (PMID 38672648, 2024).
pericardial effusion (1 paper, 2022). Fluid collection within the pericardial sac, usually due to inflammation.
periodontal disease (1 paper, 2024). "An overexpression of CTNNB1, FOS, JUN, GRB2, PIK3CA, and PIK3R1 may affect the cell cycle, resulting in excessive cell proliferation, and malignant transformation, besides being related to periodontal disease development and progression." (PMID 39517401, 2024).
pilocytic astrocytoma (1 paper, 2016). Pilocytic astrocytoma is a rare subtype of low-grade glioma of the central nervous system characterized by a well circumscribed, often cystic, brain tumor with a discrete mural nodule and long, hair-like projections that extend from the neoplastic astrocytes. "Several other studies have verified the benefit of CTNNB1 and BRAFV600E in the differential diagnosis of sellar lesions and we support this statement, with the caveat that V600E mutations may also occur for example in sellar pilocytic astrocytomas, and thus supportive histology is also required." (PMID 26927026, 2016).
pineal tumours (1 paper, 2009). "Of 28 scorable primary CNS PNETs 10 displayed CTNNB1 nuclear staining (36%), which included one pineal tumour (out of five)." (PMID 19293793, 2009). "The cellular location of CTNNB1 was investigated in 49 tumours in the CNS PNET cohort (including 7 pineal tumours), which included 42 primary samples." (PMID 19293793, 2009).
pineoblastoma (1 paper, 2009). Pineoblastoma is a rare, malignant type of supratentorial primitive neuroectodermal tumor (sPNET), found mainly in children (less than 10% of cases are reported in adults), and located in the pineal region of the brain but that can metastasize along the neuroaxis. "In the other four (including the pineoblastoma), low CTNNB1 nuclear positivity was seen." (PMID 19293793, 2009).
placental disorders (1 paper, 2025). "Abnormal expression of CTNNB1 and CDH1 was linked to pregnancy-related placental disorders." (PMID 40150405, 2025).
Pleural effusion (1 paper, 2021). The presence of an excessive amount of fluid in the pleural cavity. "In our study, relapses of tumors with CTNNB1 mutations usually occurred in distant organs (two cases brain, one case adrenal gland, one case multiple contralateral lung nodules, and one case pleural effusion)." (PMID 34298845, 2021).
polycystic kidney disease (1 paper, 2015). A usually autosomal dominant and less frequently autosomal recessive genetic disorder characterized by the presence of numerous cysts in the kidneys leading to end-stage renal failure. "NEK1 and CTNNB1, together with AXIN1, GSK3B and TSC2, participate in the Wnt signaling pathway in urological cancer cells and polycystic kidney disease (PKD)." (PMID 26317783, 2015).
prostate adenocarcinoma (1 paper, 2022). "Consistently, the co-expression analysis in TCGA PanCancer Atlas revealed that SCAND1 and MZF1 expression was negatively correlated with EMT driver genes, including CTNNB1, ZEB1, ZEB2 and TGFBRs, in prostate adenocarcinoma specimens." (PMID 36552758, 2022).
psychosis (1 paper, 2018). "Amphetamine doses that are known to induce psychosis also decrease levels of Ctnnb1, but the effect of therapeutic doses of amphetamines on Wnt signaling in an ADHD-like brain, to the best of our knowledge has not been explored." (PMID 30110355, 2018).
Q fever (1 paper, 2019). A bacterial infection caused by Coxiella burnetii. "We found that the expression of CTNNB1 mRNA coding for β-cat in PBMCs of Q fever patients was significantly reduced in acute Q fever (n = 15; p = 0.0029) compared to healthy controls and patients with persistent Q fever." (PMID 31293984, 2019). "Herein, we evidenced for the first time that sE-cad is released from cell membrane in patients with Q fever, and that C. burnetii infection modulates the expression of the CDH-1/E-cadherin and CTNNB1/β-catenin genes and the cell-surface expression of E-cad on monocytes during Q fever." (PMID 31293984, 2019).
rectal tumors (1 paper, 2022).
Renal cyst (1 paper, 2023). A fluid filled sac in the kidney. "In ADPKD, signaling pathways activated in renal cysts by loss of PKD1 include many known to be activated and growth-promoting in cancer including WNT/CTNNB1, PI3K/AKT, mTOR/S6K, RAF/MEK/ERK, SRC, MYC, AURKA, and others." (PMID 37542051, 2023).
retinoblastoma (1 paper, 2021). A malignant tumor that originates in the nuclear layer of the retina. "Also, SHH and WNT pathways were significantly enriched in IO-MEPLs compared to retinoblastomas with increased expression levels of CTNNB1 and SMO." (PMID 34785636, 2021).
rheumatoid arthritis (1 paper, 2020). A chronic, systemic autoimmune disorder characterized by inflammation in the synovial membranes and articular surfaces.
Right ventricular cardiomyopathy (1 paper, 2020). Right ventricular dysfunction (global or regional) with functional and morphological right ventricular abnormalities, with or without left ventricular disease. "The pathways involved in the antagonistic GSK-126 group were the bacterial invasion of epithelial cell pathway and the arrhythmogenic right ventricular cardiomyopathy (ARVC) pathway, involving proteins of the PSMD family such as CTNNB1, CTNNA1, PHB1, and SUCLG2." (PMID 33195195, 2020).
serous cystadenoma (1 paper, 2022). A serous neoplasm in which the cysts and papillae are lined by a single layer of cells without atypia, architectural complexity or invasion. "In serous cystadenomas, the absence of CTNNB1 mutation can be used to distinguish them from SPNs." (PMID 35299739, 2022).
small intestinal tumors (1 paper, 2021). "The majority (93.8%) of small intestinal tumors displayed no relevant nuclear β-catenin translocation and the only tumor showing a nuclear IHC-signal did not harbor a CTNNB1 mutation." (PMID 34885050, 2021).
Solid Pseudopapillary Neoplasm of the Pancreas (1 paper, 2021). A low-grade malignant neoplasm that arises from the exocrine pancreas. "LEF1 IHC has been recently introduced as a useful tool in the diagnosis of solid-pseudopapillary neoplasm of the pancreas, a tumour with a gain-of-function mutation in CTNNB1." (PMID 34420090, 2021).
startle disease (1 paper, 2016). "Consequently CTNNB1 should be added to the growing list of genes to be considered as a cause of startle disease or syndromic hyperekplexia." (PMID 26968164, 2016).
steatosis (1 paper, 2018). Increased lipid within the cytoplasm of cells. "Although others have found that genes involved in Wnt signaling may be downregulated in NASH27, our study showed upregulated expression of Wnt signaling genes in NASH compared to steatosis, including Ctnnb1 and Myc." (PMID 30367044, 2018).
tendinopathy (1 paper, 2011). "Additionally, tendinopathy tissue showed differential expression of other WNT pathway genes, including increased expression of CTNNB (1.5-fold), WNT5a (2.7-fold), and FZD1 (1.7-fold) and decreased expression of LRP5 (0.59-fold) and FRZB (0.35-fold)." (PMID 21539748, 2011).
thyroid tumours (1 paper, 2020). "Focusing only on thyroid tumours with TERT promoter mutations and liver tumours with CTNNB1 mutations, we compared the proportions of polyclonal vs. monoclonal tumours between the sexes." (PMID 32859912, 2020).
transitional cell carcinoma of bladder (1 paper, 2021).
tubulovillous adenoma (1 paper, 2021). An epithelial neoplasm morphologically characterized by the presence of a villous and a tubular architectural pattern. "Conventional tubular or tubulovillous adenomas (TVAs) are ligand independent, and their tumor-initiating APC or CTNNB1 mutations likely occur in stem cells." (PMID 34788095, 2021).
type 1 diabetes (1 paper, 2011). "Our study was designed to assess association of common single nucleotide polymorphisms (SNPs) in four key genes of the canonical Wnt/β-catenin signalling pathway (AXIN2, CTNNB1, LRP5 and LRP6) with DN using a case-control design involving 1467 individuals with type 1 diabetes." (PMID 21876774, 2011).
venous thromboembolism (1 paper, 2022). Occlusion of the lumen of a vein by a thrombus that has migrated from a distal site via the blood stream. "Somatic tumor mutations in STK11, KRAS, CTNNB1, KEAP1, CDKN2B and MET, which were reported to be associated with cancer-induced venous thromboembolism in an independent study, were infrequent in OSCC." (PMID 35053621, 2022).
viral myocarditis (1 paper, 2025). Myocarditis that is caused by an infection with a viral agent. "Our data proposed that CTNNB1 knockdown can lead to activation of the viral myocarditis pathway following SARS-CoV-2 infection." (PMID 40136643, 2025).
vulvar tumors (1 paper, 2019). "All triple-gene mutant (PTEN+PI3K+CTNNB1) mice were euthanized by 75 d after Ad-Cre injection because of health issues due to blockage of the urinary tract by rapidly growing vulvar tumors." (PMID 30782821, 2019).
tumor (1,026 papers, 2000 to 2026). "The p.G34E and p.T41I missense mutations accounted for around 41% of all Ctnnb1 mutations; tumours with p.G34E mutations also had a higher overall mutation burden compared with tumours with other exon-3 mutations." (PMID 41339549, 2026). "As with the p.I35S mutations in Ctnnb1, this suggests that subsequent loss of Fbxw7 promotes tumour formation by a subset of transformants with existing N-terminal truncations of APC." (PMID 41339549, 2026). "Recent genome sequencing efforts of HCC patient cohorts revealed that mutations in AXIN1 and CTNNB1 are mutually exclusive and associate with distinct tumor characteristics, aggressiveness, and clinical prognosis." (PMID 41550750, 2026). "In human HCC, 81% of CTNNB1-mutated tumours exhibit MYC copy number gain along with significantly increased MYC gene expression." (PMID 41261129, 2026). "Biomarker-driven selection, circulating tumor DNA for minimal residual disease, resistance-associated alterations (e.g., CTNNB1), and etiology-linked immune phenotypes, will be central to optimizing patient selection and treatment sequencing." (PMID 42040612, 2026). "Sertoli cell tumour NOS is largely driven by gain‐of‐function CTNNB1 mutations, which are identified in ~70% of these neoplasms overall." (PMID 41384702, 2026). "While each priming event promoted tumour development by both Apc and Ctnnb1 mutations, the ratios varied." (PMID 41339549, 2026). "These analyses confirmed that tumours arising from priming followed by ENU-induced mutagenesis were dominated by single-base mutations of either Ctnnb1 or Apc." (PMID 41339549, 2026). "Tumours developing under rescue conditions were still predominantly driven by Apc and Ctnnb1 mutations." (PMID 41339549, 2026). "Permissive fields promote transformation by Ctnnb1 and Apc mutations that are, respectively, poor or competent tumour initiators in a WT context." (PMID 41339549, 2026). "In these tumours, CTNNB1 variants are typically present with multiple concurrent chromosomal aneuploidies and regional or focal amplification events involving cancer‐relevant genes such as MDM2 and TERT." (PMID 41384702, 2026). "Some studies suggest that CTNNB1 mutations correlate with less aggressive tumor behavior, reduced invasiveness, lower serum alpha-fetoprotein (AFP) levels, and better-differentiated HCC." (PMID 40243493, 2025). "For instance, HCCs with CTNNB1 mutations are often associated with higher tumor grades and poorer prognoses 5,23." (PMID 40765562, 2025). "Its activation is often driven by mutations in CTNNB1, resulting in enhanced cell proliferation and tumor formation." (PMID 40765562, 2025). "In high-grade tumors, CTNNB1 mutations disrupt cellular adhesion mechanisms, allowing cancer cells to break away from the primary tumor mass, invade surrounding tissues, and potentially spread to distant organs." (PMID 40072110, 2025). "When coupled with CTNNB1 mutations, which activate the Wnt/β-catenin pathway, dual activation of these pathways can lead to enhanced tumor growth and resistance to treatment." (PMID 40072110, 2025). "As expected from the VAF distribution of Ctnnb1 mutations and the high malignancy score of this gene, tumour-associated SNVs reached high VAFs corresponding to large tumours." (PMID 40386410, 2025). "One preclinical study has found a potential capability of Tegavivint in nuclear β-catenin inhibition, which is an essential anti-tumor effect of the drugs in treating DF patients with CTNNB1 mutation." (PMID 40008005, 2025).